EGR1 (early growth response 1)
Diseases named in the same sentence as EGR1 in open-access papers (continued):
Sharing a sentence is not in itself a finding about the gene and the disease.
glioma (continued). "GDNF mRNA expression was significantly increased by Egr-1 overexpression in C6 glioma cells." (PMID 28187447, 2017). "Then, expression of EGR1 gene was knocked down by RNAi in several glioma cell lines." (PMID 29246166, 2017). "Their results indicated that EGR1 acted as a tumor suppressor in glioma." (PMID 29246166, 2017). "Furthermore, to observe the effect of EGR1 on growth of glioma, heterotopic mouse tumors were established from glioma U251 cells and U251SLC cells." (PMID 29246166, 2017). "Knockdown of EGR1 by RNAi was able to inhibit the growth of glioma cells." (PMID 29246166, 2017). "The effect of Egr-1 overexpression on GDNF transcription in glioma cells was examined to test this hypothesis." (PMID 28187447, 2017). "In addition, we previously found that GDNF transcription was significantly decreased by the knockdown of Egr-1 in C6 glioma cells." (PMID 28187447, 2017). "So, we wondered if stably alter EGR1 expression levels would influence glioma proliferation." (PMID 29246166, 2017). "We therefore hypothesized that Egr-1 expression might also be abnormally increased in high-grade glioma cells and that this transcription factor could mediate histone hyperacetylation-induced high-level GDNF transcription." (PMID 28187447, 2017). "EGR1 silencing inhibited proliferation and induced G1 phase arrest in glioma cells." (PMID 29246166, 2017). "It was also reported that the suppression of the transcription factor EGR1 is a common event in gliomas, resulting cell proliferation, so the upregulation could contribute to the inhibition effects in GMB cells upon REST silencing." (PMID 27153061, 2016). "However, the role of EGR1 in glioma has rarely been reported in the literature." (PMID 40936205, 2025). "Furthermore, GINS2 regulated the malignant phenotype and TMZ sensitivity of glioma cells, mostly by promoting DNA damage repair by affecting the mRNA stability of early growth response factor 1 (EGR1), which in turn regulates the transcription of epithelial cell-transforming sequence 2 (ECT2)." (PMID 38467631, 2024). "Furthermore, knockdown of SerpinB3 in LN-18 and U251 glioma cells reduced Myc and EGR1 expression." (PMID 34696771, 2021). "We next wondered whether EGR1 over-expression promoted the growth of glioma cells." (PMID 29246166, 2017). "WB analysis revealed that, compared with those in normal glial cells, the contents of EGR1 and HOXB9 in glioma cells obviously increased (0.690 ± 0.024 vs. 0.124 ± 0.008, 0.719 ± 0.007 vs. 0.114 ± 0.015; *p < 0.05)." (PMID 40936205, 2025). "A cell model test revealed that in glioma cells overexpressing miR‐192, the protein levels of EGR1 and HOXB9 were significantly lower (EGR1: 0.217 ± 0.010 vs. 0.710 ± 0.041; HOXB9: 0.419 ± 0.004 vs. 0.794 ± 0.064; * p < 0.05)." (PMID 40936205, 2025). "In conclusion, GINS2 regulated the TMZ sensitivity of glioma through the EGR1/ECT2 axis as well as the DDR pathway, and the GINS2–EGR1–ECT2 pathway has clinical implications for predicting the prognosis of glioma patients." (PMID 38467631, 2024). "In this study, we performed ex vivo experiments to discover that GINS2 regulated the malignant phenotype and TMZ sensitivity of glioma cells, likely by promoting DDR through the early growth response protein 1 (EGR1)/ECT2 axis." (PMID 38467631, 2024).
glioma (continued). "Similar to IL-6, knockdown of TMEM44-AS1 reduced the expression of EGR1 in LN-18 and U251 cells, whereas TMEM44-AS1 overexpression increased EGR1 expression in SF126 glioma cells." (PMID 34696771, 2021). "The effects of Egr-1 overexpression on histone acetylation, Egr-1 binding to GDNF promoter II, RNA POL II recruitment, and GDNF transcription in curcumin-treated C6 glioma cells were examined by gene overexpression, ChIP, and real-time PCR studies." (PMID 28187447, 2017). "Acetylation was significantly higher in the Egr-1 on-target region of GDNF promoter II (P < 0.01) and the off-target region (P < 0.05) in high-grade glioma tissue compared with normal brain tissue." (PMID 28187447, 2017). "Next, the effects of Egr-1 overexpression on Egr-1 binding to GDNF promoter II, RNA POL II recruitment, and GDNF transcription in C6 glioma cells were determined by gene overexpression, ChIP, and real-time PCR." (PMID 28187447, 2017). "Our next study will focus on the how Egr-1 and RNA POL II jointly promote high-level GDNF transcription in high-grade glioma cells." (PMID 28187447, 2017). "The results showed that although both Egr-1 and RNA POL II were present in the nuclei of C6 glioma cells with local overlapping regions, they were not bound to each other." (PMID 28187447, 2017). "This indicates that the regulation of GDNF induced by overexpressed Egr-1 and RNA POL II in high-grade glioma cells is dependent on histone hyperacetylation of GDNF promoter II." (PMID 28187447, 2017). "CPZ inhibited cell-cycle progression in rat glioma C6 cells by inducing p21Waf/Cip1/Egr1 expression and induced autophagic cell death by inhibiting the AKT/mTOR pathway in human glioma U87-MG cells." (PMID 26363315, 2015). "ETS-1 protein is not only differentially expressed in astrocytes and astrocytoma cells but also regulates various targets such as Egr-1, cathepsin B and the urokinase-type plasminogen activator besides PP2A-Aα in gliomas." (PMID 19750005, 2009). "Similarly, compared with those in low‐grade glioma samples (WHO I–II), EGR1 and HOXB9 levels were also significantly increased in high‐grade (WHO III–IV) glioma samples (0.463 ± 0.026 vs. 0.249 ± 0.013, 0.543 ± 0.018 vs. 0.233 ± 0.015; *p < 0.05)." (PMID 40936205, 2025). "This regulatory factor could inhibit the expression of downstream EGR1 and HOXB9 through targeted binding, thus forming a semi‐open loop that could regulate the malignant phenotypes of glioma." (PMID 40936205, 2025). "Immunohistochemical staining of isolated glioma samples revealed that, compared with those in the NC group, EGR1 and HOXB9 protein levels in glioma samples from the OE miR‐192 group were obviously lower (U87 group: 0.35 ± 0.07 vs. 1.10 ± 0.14; U251 group: 0.40 ± 0.14 vs. 1.25 ± 0.07; *p < 0.05)." (PMID 40936205, 2025). "In glioma, ELK1 has also been investigated as a promoter of EGR1 transcription." (PMID 40862737, 2025). "Our research revealed that both EGR1 and HOXB9 promote MT in glioma cells." (PMID 40936205, 2025). "In gliomas, TMEM44-AS1 binds to SerpinB3 and activates myc and EGR1\IL-6 signaling." (PMID 38040698, 2023). "Egr-1 is a key transcription factor for GDNF gene activation and is involved in histone hyperacetylation-mediated high-level GDNF transcription in glioma cells." (PMID 28187447, 2017). "In glioma, EGF or substance P can activate EGFR, which activates ERK and EGR1 biosynthesis." (PMID 29246166, 2017). "Moreover, EGR1 correlated with stemness markers and proliferation by orchestrating a PDGFA-dependent growth-stimulatory loop in primary glioma stem-like cells." (PMID 29246166, 2017).
glioma (continued). "It was therefore speculated that Egr-1 might have a similar effect, which led us to examine Egr-1 binding to RNA POL II in C6 glioma cells." (PMID 28187447, 2017). "EGR-1 is commonly suppressed in gliomas in human glioma independent of p16/INK4a/ARF and Mdm2." (PMID 36233659, 2022). "Some studies have found that overexpression of EGR-1 may participate in the recruitment of RNA pol II to the GDNF promoter in a non-binding manner, and thus is involved in the regulation of GDNF transcription in glioma cells." (PMID 34557404, 2021). "In conclusion, highly expressed Egr-1 may be involved in the recruitment of RNA POL II in GDNF promoter II in a non-binding manner, and thereby involved in regulating GDNF transcription in high-grade glioma cells." (PMID 28187447, 2017). "In accordance, ectopic TMEM44-AS1 increased Myc and EGR1 in both mRNA and protein levels, but not in SerpinB3-knockdown SF26 glioma cells." (PMID 34696771, 2021). "Egr-1 and RNA POL II co-existed in the nucleus of C6 glioma cells, with overlapping regions, but they were not bound to each other." (PMID 28187447, 2017). "Collectively, these findings indicate that in high-grade glioma cells, highly expressed Egr-1 may be involved in recruiting RNA POL II in GDNF promoter II in a non-binding manner, suggesting that Egr-1 helps regulate high-level GDNF transcription." (PMID 28187447, 2017).
colon carcinoma (46 papers, 2008 to 2025). "Our results report for the first time the dynamic interplay between Sdc-1 and HPSE in stemness-associated colon cancer via a signaling axis involving early growth response protein 1 (EGR1), FAK, and Wnt." (PMID 32477959, 2020). "In this study, we provide evidence that loss of P-bodies occurs in colon tumors, which is consistent with a concurrent loss of EGR1 and TTP." (PMID 26343742, 2015). "Further studies connecting these links between EGR1 with the loss of TTP in colon cancer is currently under investigation." (PMID 26343742, 2015). "Our data now show that EGR1 is downregulated in colon tumor tissue consistent with loss of TTP expression." (PMID 26343742, 2015). "Our data indicating a link existing between EGR1 and TTP suggest that the loss of EGR1 may be a novel contributing factor influencing P-body assembly in colon tumors." (PMID 26343742, 2015). "Studies have confirmed that activation of receptors for advanced glycation end products (RAGEs) in other diseases, such as liver ischemia/reperfusion injury and colon cancer, can stimulate the transcription of the Egr1 and AP-1 families." (PMID 38409074, 2024). "In liver cancer, PGK1 suppresses cell death through modulation of PRAS40, while in colon cancer, it upregulates the expression of EGR1, a metastasis-related factor." (PMID 38163864, 2024). "EGR1 showed anti-tumor activity in colon cancer, hepatocarcinoma, leukemia, human fibrosarcoma, etc., which was not consistent with our study." (PMID 36932397, 2023). "EGR1 also suppressed colon cancer progression by a PTEN-EMT pathway, which seems to contradict our study." (PMID 36932397, 2023). "In contrast, a recent study showed that increased levels of EGR1inhibited colon cancer cell proliferation, migration, and invasion, whereas knocking down EGR1 increased these parameters." (PMID 36433652, 2022). "Our results demonstrate that mPGES1 is induced by COX-2 overexpression, via autocrine PGs release, likely PGF2α through an EGR1-dependent mechanism in colon carcinoma." (PMID 32410997, 2020). "Meanwhile, our previous study showed that mindin attenuates colon cancer progression by blocking angiogenesis via Egr‐1–mediated regulation in human cancer cell lines." (PMID 32614521, 2020). "We previously reported that APE1 regulated GFRα1 expression via NF-κB and enhanced pancreatic cell migration and neuronal cell survival, and it also participated in JAGGED1/Notch signaling in colon cancer progression by regulating Egr-1." (PMID 32438692, 2020). "On the other hand, we previously reported that mindin attenuated human colon cancer development by blocking angiogenesis through Egr‐1–mediated regulation." (PMID 32614521, 2020). "The oncogenic role of miR183 has also been revealed in a recent study by targeting the transcription factor EGR1 and promoting tumor cell migration in different types of cancer, such as sarcomas and colon tumors." (PMID 25856466, 2015). "In colon cancer, it has been suggested that EGR1 serve as a tumor suppressor that is downregulated or lost as a consequence of APC mutation and the subsequent nuclear accumulation of β-catenin." (PMID 26343742, 2015). "The authors demonstrated that the reduction of EGR-1 activity plays a critical role in the inhibition of EGFR expression in human colon cancer cells." (PMID 23251236, 2013). "Yong Song Gho (POSTECH, Korea) presented proteomic and genomic studies, showing a pro-angiogenic profile of colon cancer–derived EVs activating endothelial cells and macrophages by regulating the function of the early growth response protein 1 (EGR1)." (PMID 26082071, 2012). "The considerable level of basal Egr-1 expression in colon carcinoma cells can maintain high c-FLIP expression levels, in particular c-FLIPs, and can thus reduce TRAIL sensitivity." (PMID 20087343, 2010).
colon carcinoma (continued). "In conclusion, this study shows that Egr-1 regulates the expression of c-FLIP in colon carcinoma cells and probably this mechanism contributes to Egr-1-mediated TRAIL resistance." (PMID 20087343, 2010). "In this report we show that the immediate early gene, Egr-1, is constitutively expressed in colon cancer cells and further induced in response to rhTRAIL by both DR4 and DR5." (PMID 20087343, 2010). "Egr-1 is constitutively expressed in colon cancer cells and further induced upon activation of DR4 or DR5." (PMID 20087343, 2010). "Compared to normal tissues, the expression of EGR1 decreased in colon cancer, ovarian cancer, and liver cancer tissues, and the ectopic expression of the EGR1 gene could reduce the migration of cancer cells." (PMID 34889888, 2021). "Interestingly, this secreted PGF2α was able to increase mPGES1 but also COX-2 in colon carcinoma cells, via FP receptor and EGR1, further enhancing PGE2 levels indicating a positive feedback loop between COX-2/mPGES1/PGE2 and PGF2α." (PMID 32410997, 2020). "Interestingly, sulindac sulfide (or troglitazone)-mediated NAG-1 up-regulation is dependent on the transcription factor EGR-1 in colon cancer cells." (PMID 32928152, 2020). "A pharmacological agent that coordinately upregulated GDF15 and EGR1 in a colon cancer cell line also activated transcription at a region in the GDF15 promoter containing 2 experimentally validated EGR1 binding sites, suggesting that EGR1 is a direct transcriptional regulator of GDF15." (PMID 32310257, 2020). "EGR1can promote proliferation of colon cancer cells via the EGR1/AE2/P16/P-ERK signaling pathway." (PMID 31500382, 2019). "In kidney and colon cancer cells, EGR-1 induced TGF-β1 to suppress growth and tumorigenicity." (PMID 29216821, 2017). "Additionally, miR-183-5p functions as an oncogene by targeting the transcription factor EGR1 and promoting colon cancer cells migration." (PMID 26462034, 2015). "Similarly, infiltrating MDSC in both breast and colon cancers have been predicted to be highly enriched in the EGR-1-regulated signaling." (PMID 25294811, 2014). "Curcumin has been demonstrated to suppress colon cancer cell development by lowering EGFR expression, which is mediated by a decrease in Egr-1 activity in Caco2 and HT29 colon cancer cells." (PMID 35530318, 2022). "In colon cancer, curcumin downregulated the EGFR gene expression by suppressing the early growth response-1 (egr-1) gene and the transactivation activity of Egr-1, a transcription factor that binds to the egfr promoter." (PMID 34867402, 2021). "In colon cancer, KLF12 promotes the growth of colorectal cancer through EGR1 (early growth response protein 1)." (PMID 34644678, 2021). "Mutagenesis and trans-activation studies have previously shown that EGR1 binds to the HPSE promoter and up-regulates HPSE transcription in colon cancer cells." (PMID 32477959, 2020). "CUR was found to suppress the expression of EGFR, mediated by the reduction of Egr-1 activity in Caco2 and HT29 colon cancer cells, inhibiting colon cancer cell growth." (PMID 30890933, 2019). "Suppresses the expression of EGFR, mediated by the reduction of Egr-1 activity in Caco2, and HT29 colon cancer cells, inhibiting colon cancer cell growth." (PMID 31801262, 2019). "Recently, in an established xenograft mouse model of colon cancer, the drug ML264 efficiently inhibited growth of the tumor within 5 days of treatment by inhibiting the expression of KLF5 and EGR1, a transcriptional activator of KLF5." (PMID 28915599, 2017). "Our study found that Egr-1 is not only rapidly induced by TRAIL, but is also constitutively expressed at a relatively high level in many colon carcinoma cell lines." (PMID 20087343, 2010). "Analysis of Egr-1 protein expression in colon carcinoma cell lines (Colo205, HCT15 and HCA7) showed high basal expression of Egr-1 and its further induction in response to rhTRAIL, DR4- and DR5-agonistic antibodies." (PMID 20087343, 2010).
colon carcinoma (continued). "As well, NAG-1 induction wasalso observed in colon cancer cells treated with troglitazone or 15d-PGJ2.Importantly, both agents induce NAG-1 expression through an EGR-1-dependentmechanism." (PMID 18615184, 2008). "Moreover, miR-183 has been further emphasized in previous investigations as an oncogenic factor that regulates 2 tumor suppressor genes including EGR1 and PTEN in synovial sarcoma, rhabdomyosarcoma, and colon cancer." (PMID 33653339, 2021). "A substantial fraction of the peaks was overlapped with those obtained with EGR1‐ChIP‐seq in three other cell lines H1ES (an ES cell line), HCT116 (a colon cancer cell line), and K562 (Fig EV5 A and B), further indicating interaction between LDB2 and EGR1 proteins." (PMID 33656268, 2021). "In colon cancer cells, EGR-1 wasinduced dramatically by troglitazone but not by other PPARγ ligands.Inhibition of ERK phosphorylation abolished EGR-1 induction by troglitazone,suggesting an ERK-dependent induction of EGR-1." (PMID 18615184, 2008). "Moreover, we identified relevant signaling pathways (FAK, Wnt, Notch) and transcription factors (Egr1, TCF4), as constituents of this regulatory circuit, which paves the way for a more efficient combinatorial targeting of colon cancer in the context of therapeutic resistance." (PMID 32477959, 2020). "In contrast, there was no enrichment of hnRNP K at the Egr1 promoter, which is active in mESCs and was shown to be bound by hnRNP K only upon serum stimulation in the HCT116 colon cancer cell line." (PMID 25611934, 2015).